ATF2 (activating transcription factor 2)
Diseases named in the same sentence as ATF2 in open-access papers (continued):
Sharing a sentence is not in itself a finding about the gene and the disease.
melanoma (continued). "First, phospho-ATF-2 is expressed at high levels in B16 melanoma cells, and the ability of RA to inhibit ATF-2 phosphorylation is a slow process." (PMID 18269766, 2008). "The rationale for examining ATF-2 was to discover how RA increases AP-1 activity in B16 melanoma cells." (PMID 18269766, 2008). "Recently, it has been found that activating transcription factor 2 (ATF-2) is responsible, at least in part, for resistance of melanoma to chemo- and radiotherapy." (PMID 18269766, 2008). "The inhibition of ATF-2 phosphorylation correlated with the ability of RA to sensitize the B16 melanoma cells to the growth inhibitory activity of the cancer chemotherapeutic agent taxol." (PMID 18269766, 2008). "RA treatment of B16 melanoma cells reduced ATF-2 phosphorylation, and evidence was obtained that this action was mediated through the inhibition of p38 MAP kinase activation." (PMID 18269766, 2008). "The transcription factor ATF2 has been shown to induce therapy resistance to melanoma." (PMID 38611028, 2024). "They found that ATF2 activation via protein kinase Cε (PKCε) phosphorylation may have led to more advanced and metastatic forms of melanoma." (PMID 37955015, 2023). "Therefore, it will be interesting to evaluate the regulatory role of ATF2 in NLRP1-mediated targeted therapy resistance in melanoma." (PMID 33396632, 2020). "Importantly, an anti-inflammatory role of ATF2 in cancer has recently been established whereby PKCε-mediated activation of ATF2 directly inhibits IFNβ expression and type I interferon signaling in melanoma." (PMID 32117236, 2020). "ATF2 is a transcription factor with emerging regulatory roles in inflammatory signaling and was recently shown to inhibit IFNβ expression and type I interferon signaling in melanoma." (PMID 32117236, 2020). "Treatment with LMB inhibits nuclear export of ATF2 in melanoma cells." (PMID 30497386, 2018). "ATF2 acts as an important oncogene in prostate cancer, melanoma, non-small cell lung carcinoma and pancreatic cancer, while ATF2 exhibits tumor suppressor functions in nonmalignant skin and breast cancer, suggesting a context-dependent role for ATF2 in cancer biology." (PMID 29996942, 2018). "This leads to mitochondrial translocation of ATF2 and subsequent apoptosis in melanoma cells." (PMID 30497386, 2018). "Recent studies have found that ATF2 is a phosphorylation substrate of PKCε in melanoma cells, but it is unknown whether this phosphorylation occurs in neurons." (PMID 30497386, 2018). "The mechanism by which ATF2 regulates Bim phosphorylation in melanoma remains to be elucidated." (PMID 26462148, 2015). "Furthermore, the forced expression of cytoplasmic ATF2 peptides induces melanoma cell death and thereby reduces the transcriptional activity of endogenous ATF2." (PMID 25852302, 2015). "Furthermore, we show that ectopic cytosolic expression of ATF2 restored sensitivity to vemurafenib in BRAF inhibitor-resistant melanoma cells, suggesting that BRAF inhibitor-resistant cells indeed maintain their addiction to the ATF2 pathway." (PMID 26462148, 2015). "Thus, high levels of PKCɛ in melanoma are responsible for promoting chemoresistance and tumorigenesis by nuclear targeting of ATF2." (PMID 24727247, 2014). "Moreover, inhibition of PKCɛ-mediated ATF2 phosphorylation resulted in cytoplasmic targeting of ATF2 and reduced oncogenic properties of melanoma cells." (PMID 24727247, 2014). "In contrast, ATF2 inhibition in melanoma cells increased c-Jun expression." (PMID 23800081, 2013). "Cyclin D1 is activated by ATF-2 in proliferating murine melanoma cells." (PMID 21429205, 2011). "Notably, the melanocytes and 2/4 melanoma cell lines revealed ATF2 effect on MITF expression is SOX10-dependent (WM1361, WM793)." (PMID 21203491, 2010).
melanoma (continued). "Our quest to understand mechanisms underlying ATF2 activity in this process led us to identify an important role for ATF2 regulation of MITF, an important regulator of melanocyte biogenesis and a factor implicated in melanoma progression." (PMID 21203491, 2010). "Indeed, expression of transcriptionally inactive ATF2 or peptides that attenuate endogenous ATF2 activity inhibits melanoma development and progression in xenograft models." (PMID 21203491, 2010). "While findings presented here position ATF2 as an oncogene functioning in melanocyte transformation and melanoma development, earlier studies from our laboratory and others suggest that in keratinocytes and mammary glands, ATF2 elicits a tumor suppressor function." (PMID 21203491, 2010). "Similarly, inhibition of ATF2 transcription in human melanoma 1361 cells increased SOX10 and FOXD3 transcription, albeit, to a lesser degree (3- and 1.5-fold, respectively) compared with human melanocytes." (PMID 21203491, 2010). "MITF and SOX10 mRNA levels in melanocytes and melanoma cell lines following ATF2 KD." (PMID 21203491, 2010). "Analysis was limited to melanocytes, since only one melanoma formed in the ATF2 mutant group." (PMID 21203491, 2010). "Here we demonstrate that high nuclear ATF2/MITF ratios are associated with poor prognosis in primary melanomas, but not with metastatic melanomas." (PMID 21203491, 2010). "Primary melanoma specimens that exhibit a high nuclear ATF2-to-MITF ratio were found to be associated with metastatic disease and poor prognosis, further substantiating the significance of MITF control by ATF2." (PMID 21203491, 2010). "We therefore assessed whether SOX10, which positively regulates MITF and whose transcription markedly increases in melanocytes and melanoma cells in which ATF2 expression is inhibited, may mediate ATF2 effect on MITF transcription." (PMID 21203491, 2010). "A possible link between the presence of ATF2 in repair foci in most melanoma cells points to the possible presence of activated DNA damage response which may be associated with genomic instability —aspects that will be explored in future studies." (PMID 21203491, 2010). "In addition, the melanoma cells had a much higher amount of phosphorylated (active) ATF-2 than the immortalized melanocytes." (PMID 18269766, 2008). "Although high activity of ATF-2 has not been directly implicated in tumorigenesis, published data suggest that high ATF-2 activity might be important in reaching or maintaining the malignant state of melanomas." (PMID 18269766, 2008). "Therefore, we conclude that the higher MW form of ATF-2 is highly phosphorylated in the melanoma cells." (PMID 18269766, 2008). "Since ATF-2 activity appears to be involved in resistance of melanoma to chemotherapy, we tested the hypothesis that treatment of the melanoma cells with RA would sensitize them to the growth-inhibitory effect of taxol." (PMID 18269766, 2008). "In melanoma, activated ATF-2 confers resistance to radiation and chemotherapeutic agents." (PMID 18269766, 2008). "Therefore we hypothesized that since RA inhibited ATF-2 phosphorylation, it would increase the sensitivity of mouse melanoma cells to chemotherapeutic agents." (PMID 18269766, 2008). "When ATF2 activity is low, SOX10 is highly expressed (phase 1‐ON), leading to high miR‐204 and MITF levels that make melanoma cells show a melanocytic or intermediate phenotype." (PMID 40458894, 2025). "In melanoma, ATF2 downregulation upregulates MITF via SOX10, transforming melanoma into a metastatic phenotype." (PMID 40458894, 2025). "In metastatic melanoma, although the expression of FUK is suppressed by the PKCε-ATF2 pathway, the ectopic expression of FUK or treatment with L-fucose significantly inhibits melanoma cell migration/invasion in vitro and lung metastasis in mouse models." (PMID 29924834, 2018).
melanoma (continued). "Taken together, we showed that mitochondrial ATF2 is involved in the induction of apoptosis and BRAF inhibitor resistance in some melanoma cell lines." (PMID 26462148, 2015). "Several melanoma cell lines, B16F10, K1735M2, A375 and A375-R1, were treated with paclitaxel and vemurafenib to test the function of mitochondrial ATF2 and its connection to Bim and voltage-dependent anion channel 1 (VDAC1)." (PMID 26462148, 2015). "ATF2 (activating transcription factor 2) displays inhibitory activity towards SOX10 both in melanocytes and melanoma cells, resulting in a decreased MITF transcript level." (PMID 25433395, 2015). "Activating transcription factor 2 (ATF2), one of the CREB family, is commonly found at metastatic sites and has been shown to be involved in melanoma development, especially in the HGF/SF transgenic mouse." (PMID 23878598, 2013). "Hypophosphorylated or transcriptionally inactive forms of ATF2 reduce TNF-α expression, resulting in sensitization of melanoma to treatment via increased apoptosis." (PMID 21429205, 2011). "We next assessed the effect of ATF2 on SOX10 and MITF expression in 12 additional human melanoma cell lines." (PMID 21203491, 2010). "Overall, our observations demonstrate that ATF2 plays an important role in fine-tuning those levels and support the rheostat model proposed for MITF's role in melanoma development and progression." (PMID 21203491, 2010). "The first class comprised four of the six melanoma cultures (1205Lu, WM35, WM793 and WM1361), in which MITF expression was elevated 3–6-fold following inhibition of ATF2 expression." (PMID 21203491, 2010). "Here we demonstrate that the transcription factor ATF2 negatively regulates MITF transcription in melanocytes and in about 50% of melanoma cell lines." (PMID 21203491, 2010). "Pull-down assays using biotin-tagged MITF promoter sequences harboring the CRE identified ATF2 and CREB as CRE-bound proteins in MeWo melanoma cells." (PMID 21203491, 2010). "Along these lines, the two melanoma lines (MeWo and 501 Mel) that exhibit positive regulation of MITF by ATF2 also exhibited positive regulation of SOX10 by ATF2." (PMID 21203491, 2010). "When endogenous ATF-2 expression is inhibited by ATF-derived peptides, human melanoma cells are more sensitive to UV radiation or chemical treatment, and their growth and metastasis are also inhibited." (PMID 18269766, 2008). "For instance, ATF2 plays tumor-promoting roles in melanoma, non-small cell lung carcinoma and pancreatic cancer cells, while it has tumor-suppressing activities in non-melanoma skin cancer, breast cancer, as well as in mouse orthotopic model of liver cancer." (PMID 35641966, 2022). "Dong Wei identified that ATF2, SOX2, and RAC1 are involved in the metastasis of melanoma." (PMID 33336008, 2020). "Although ATF2 has previously been reported to be a PKCε phosphorylation substrate in melanoma cells, in neuronal cells ATF2 phosphorylation by PKCε has not previously been studied." (PMID 30497386, 2018). "In melanoma and non-small cell lung carcinoma, ATF2 acts as an important oncogene, while in nonmalignant skin and breast cancer, ATF2 elicits tumor-suppressor function, suggesting a context-dependent role for ATF2 in cancer biology." (PMID 27377902, 2016). "According to these results, we speculate that there might be a signaling relationship between the ATF2 and BH3 proteins, which are involved in mitochondria-based apoptosis and BRAF inhibitor resistance in melanoma." (PMID 26462148, 2015). "ATF2 control of melanoma development is mediated, in part, through its negative regulation of SOX10 and consequently, of MITF transcription." (PMID 24743024, 2014).
melanoma (continued). "BBR inhibits melanoma cell invasion and metastasis by inhibition of COX-2, PGE2 and PGE2 receptors and several other signaling molecules such as ERK1/2, NF-κB, ATF-2 and CREB which are involved in the transcriptional regulation of matrix metalloproteinase (MMP) gene expression." (PMID 24456611, 2014). "Surprisingly, ATF2 control of melanoma development was mediated, in part, through its negative regulation of SOX10 and consequently of MITF transcription." (PMID 21203491, 2010). "We demonstrate that in the absence of transcriptionally active ATF2, melanoma formation is largely inhibited." (PMID 21203491, 2010). "Notably, about 4/12 melanoma lines revealed increase in both SOX10 and MITF expression upon KD of ATF2." (PMID 21203491, 2010). "Collectively, out of 18 melanoma lines we found that 8 (44%) retained similar negative regulation of MITF by ATF2 as observed in the melanocytes." (PMID 21203491, 2010). "To further assess whether ATF2 regulation of MITF is SOX10-dependent in melanocytes and melanoma cells, we coexpressed SOX10 in shATF2-expressing cells." (PMID 21203491, 2010). "Notably, MeWo and 501Mel lines are known to express high MITF levels compared to other melanoma lines, suggesting these cells harbor distinct mechanisms that preclude negative regulation of MITF by ATF2." (PMID 21203491, 2010). "Analysis of a MITF-Luc construct harboring a mutant SOX10 binding site revealed that ATF2 inhibition no longer elicited increased MITF transcription in human melanocytes or in melanoma cells." (PMID 21203491, 2010). "Neither BRN2 nor PAX3 transcription was elevated in melanoma cells in which ATF2 expression was inhibited." (PMID 21203491, 2010). "Importantly, ATF2-dependent negative regulation of Sox10 and consequently of MITF seen in melanocytes, but only in about 50% of the 18 melanoma cell lines studied here." (PMID 21203491, 2010). "We found that B16 mouse melanoma cells express 2–4 times more ATF-2 protein relative to non-malignant mouse melan-a cells." (PMID 18269766, 2008). "In this report we demonstrate that ATF-2 is expressed at a higher level in B16 melanoma cells when compared with an immortalized, but non-malignant, mouse melanocyte cell line." (PMID 18269766, 2008). "We found that ATF-2 protein was expressed at higher levels in B16 melanoma cells compared with non-malignant melan-a cells." (PMID 18269766, 2008). "Higher levels of ATF-2 protein were detected in malignant melanoma cells, compared with non-malignant mouse melanocytes." (PMID 18269766, 2008). "In concordance with these reports, we found that B16 mouse melanoma cells had higher levels of ATF-2 than immortalized, but non-malignant mouse melanocytes." (PMID 18269766, 2008). "We examined ATF-2 phosphorylation as an indicator of its activation in malignant melanoma cells, compared with non-malignant mouse melanocytes." (PMID 18269766, 2008). "It has been found in mouses bearing melanoma that leptin-a lipid factor in fat metabolism-binds to the upregulated leptin receptor on TILs, induces phospho-p38 MAPK activation, further activates transcription factor ATF2, ultimately increasing TIL oxidative activity and ability." (PMID 39342365, 2024). "ATF2 functions as an oncogene in melanoma but as a tumor suppressor in non-malignant skin cancer." (PMID 24727247, 2014). "Thus, Atf2md::N-RasQ61K::Ink4a−/− mice were used to assess changes in melanoma incidence in the absence of functional ATF2 over a period of up to 8 months." (PMID 21203491, 2010). "Given that ATF2 negatively regulates MITF in melanocytes of mouse and human tissues and in related melanocyte cell lines, we asked whether ATF2 also regulates MITF in human melanoma cells." (PMID 21203491, 2010).
melanoma (continued). "In order to determine whether JunB lost its ability to elicit negative regulation of SOX10 and MITF in melanoma cells where ATF2 no longer inhibited SOX10 or MITF expression, we transfected those cell lines with TAM67 and JunB alone and in combination." (PMID 21203491, 2010). "In two out of the 12 melanoma lines ATF2 affected SOX10 but not MITF transcription." (PMID 21203491, 2010). "In contrast, melanocytes infected with BRAF600E and with shATF2 formed on average about 20 colonies, indicative of loss of tumorigenicity and consistent with our initial observation that the number of melanoma tumors significantly decreases in the absence of transcriptionally functional ATF2." (PMID 21203491, 2010). "However, a previous study in B16F-10 melanoma cells showed that piperine was able to inhibit the activation of several transcription factors, including NFκB, c-FOS, cAMP response element binding (CREB) and activating transcription factor 2 (ATF-2)." (PMID 19327174, 2009). "Thus, it is likely that in addition to having more total ATF-2 protein in malignant mouse melanoma cells versus non-malignant cells, much more of the ATF-2 in melanoma cells is in the active (phosphorylated) state." (PMID 18269766, 2008). "In addition, most of the ATF-2 protein in the melanoma cells is phosphorylated (active) vs. only a small amount of phosphorylated ATF-2 in non-malignant melanocytes." (PMID 18269766, 2008). "In addition, 4-1BB co-stimulation can upregulate PGC1α expression, and activate ATF2 through the p38-MAPK pathway, thereby enhancing mitochondrial fusion and biogenesis, and ultimately promoting the immunity and memory of CD8+ T cells in mouses bearing melanoma." (PMID 39342365, 2024). "Two of the four melanoma cell lines did not reveal increased SOX10 expression, although they retained increased MITF expression, upon inhibition of ATF2 (Lu1205, WM35)." (PMID 21203491, 2010). "Melanocytes from mice lacking active ATF2 expressed increased levels of MITF, confirming that ATF2 negatively regulates MITF and implicating this newly discovered regulatory link in melanoma development." (PMID 21203491, 2010). "Using either a wild-type (WT) construct or one in which the BRN2 site was mutated, we observed increased luciferase activity following inhibition of ATF2 transcription in WM1361 melanoma, as well as in LU1205 and WM35 melanoma cells (data not shown)." (PMID 21203491, 2010). "Correspondingly, JunB, which is required for ATF2-dependent inhibition of Sox10 transcription, is no longer found on the promoter of SOX10 in melanoma cells (i.e. 501Mel) that exhibit positive regulation by ATF2." (PMID 21203491, 2010). "The mechanism by which RA increases the sensitivity of B16 melanoma cells to taxol treatment is likely to involve ATF-2 activity, because inhibitors of p38 MAPK also sensitize B16 melanoma cells to taxol's growth inhibitory activity (data not shown)." (PMID 18269766, 2008).